CXCL9 (C-X-C motif chemokine ligand 9)
Diseases named in the same sentence as CXCL9 in open-access papers (continued):
Sharing a sentence is not in itself a finding about the gene and the disease.
tumor (continued). "The CXCL9+ TAMs and SLC40A1+ TAMs were enriched in peri-tumor region, and CXCL9+ TAMs showed the highest RO/E value of 3.41." (PMID 40230843, 2025). "The increase in T cells in the TME after aCD40 treatment was possibly due to the increase in the production of chemokines such as CCL5, CCL21, CXCL9, and CXCL10 within the tumor." (PMID 40585246, 2025). "Thus, CXCL9 may have both protective and tumor-promoting effects depending on the situation." (PMID 40489865, 2025). "CXCR3, a common receptor for CXCL9 and CXCL10 recruits Th1 cells to the TME, suppressing tumour growth." (PMID 40852716, 2025). "In the early stages of tumor development, signaling molecules such as CXCL9 and IFN-β drive neutrophils toward an anti-tumor N1 phenotype." (PMID 41200171, 2025). "The CXCL-9, −10, −11/CXCR3 axis promotes tumor suppression through the recruitment of cytotoxic lymphocytes, NK cells, and NK T cells in a paracrine manner." (PMID 40447617, 2025). "By using Xenium Explorer, we confirmed strong expression of CXCL9 and CXCL13 in almost all areas around the tumour, including at sites of tumour eradication." (PMID 40670667, 2025). "One key mechanism driving immunotherapy resistance involves the exclusion of cytotoxic T cells and NK cells from the tumor, due to the downregulation of important chemokines, such as CCL5, CXCL9, or CXCL1025–27." (PMID 40562773, 2025). "A recent study classified TAMs into pro-tumor and anti-tumor subsets based on the ratio of SPP1 and CXCL9." (PMID 39858015, 2025). "Inflammatory cytokines (such as CXCL9 and CXCL10) induced by nCRT can also attract CD8+ T cells to the tumor site, enhancing their cytotoxic effect." (PMID 40936903, 2025). "In another example, the downregulation of CXCL9 in tumor-permissive CHRNA7KO mice was consistent with its upregulation by IFN-γ,29 highlighting the importance of CXCL9 in attracting T cells." (PMID 40653990, 2025). "CXCL9 and CXCL10 are induced by IFN-γ secreted from activated T cells and establish chemotactic gradients to recruit CXCR3+ CD8+ T cells to tumor niches." (PMID 40698080, 2025). "CXCL9, CXCL10, and CXCL11 interact with CXCR3 on tumor cells, immune cells, and vascular endothelial cells, influencing tumor growth, immune cell activity, and blood vessel formation." (PMID 40362215, 2025). "This conclusion is also supported by a corresponding increase in the ligands for CXCR3, CCR5 (e.g., CXCL9, CXCL10, CCL5) in both tumor and liver supernatants after treatment, whereas CXCR6 ligand (CXCL16) is higher only in the tumor." (PMID 41415437, 2025). "The upregulation of chemokine genes Ccl3, Ccl5, Cxcl9, and Cxcl10 suggests that these activated CD8+ T cells possess increased migratory capacity, allowing them to infiltrate the tumor microenvironment more effectively." (PMID 40534857, 2025). "OVs secrete chemokines, such as CXCL9 and CXCL10, which attract CAR-T cells into the tumour core, thereby enhancing T cell homing into the tumour site." (PMID 40624498, 2025). "Considering the individual loadings on PC2 and PA, we found that patients who engaged in moderate PA had lower levels of CXCL9, CXCL10, and CXCL11, known pro-inflammatory chemokines involved in immune cell migration and tumor progression." (PMID 40510182, 2025). "Further analysis showed increased production of proinflammatory interleukins such as IL‐1β and IL‐16 and accumulation of various chemotactic agents, including CCL3, CCL4, CCL5, CXCL9, CXCL10, and CXCL11, in the tumor tissue." (PMID 41221154, 2025). "Second, tumor‐homing eosinophils secrete chemokines such as CCL5, CXCL9, and CXCL10 that create chemotactic gradients for cytotoxic T lymphocytes." (PMID 41362643, 2025). "M1-type TAMs secrete factors that exert anti-tumor effects: IL-12, TNF-α, and IL-1β activate cytotoxic T cells and NK cells, and CXCL9 recruits Th1 cells and cytotoxic T cells to the TME, enhancing anti-tumor immunity." (PMID 40375990, 2025).
tumor (continued). "Posttreatment alterations included a significant increase in CXCL9+ cells and CXCL13 + T cells, particularly around tumour cells." (PMID 40670667, 2025). "Radiotherapy also upregulates the expression of CXCL9 and CXCL10 TDLNs, facilitating the recruitment of effector T cells and natural killer (NK) cells, and enhancing immune recognition and clearance of tumor cells." (PMID 40904508, 2025). "Motile tumour cells frequently overexpress MMPs, such as MMP-8 and MMP-9, which cleave chemokines like CXCL9 and CXCL10, disrupting chemotactic gradients and diminishing T-cell infiltration." (PMID 40361472, 2025). "CXCL9, a member of the CXC chemokine family, plays a critical role in immune regulation, inflammation, tumor growth, angiogenesis, and metastasis." (PMID 40936719, 2025). "Bacterial components activated chemokine production (e.g., CXCL9, CXCL10, CCL5) by tumor cells, thereby enhancing T cell infiltration." (PMID 40475782, 2025). "Within the TME, eosinophils activated by TNF-α and IFN-γ release chemokines such as CXCL9 and CXCL10, promoting CD4+ and CD8+ T cell infiltration and enhancing anti-tumor immune responses." (PMID 41200171, 2025). "The results demonstrated significantly higher mRNA expression of IFN-γ, TNF-α, IL-2, IL-12a, CXCL9, and CXCL10 in the tumor tissue of the PD-L1-KO/ZG16 overexpression group compared to the control group." (PMID 39958358, 2025). "However, despite its critical role in immune‐mediated renal injury, CXCL9 blockade has been shown to impair anti‐tumor immune responses in preclinical models, suggesting that its clinical utility may lie more in renal‐specific immune monitoring rather than therapeutic inhibition in oncology." (PMID 40810645, 2025). "The interaction between chemokines such as CXCL9, CXCL10, CXCL11, and their receptor CXCR3 is known to affect immune cell behavior, potentially enhancing tumor growth and spread." (PMID 39964621, 2025). "Downregulation of chemokines such as CXCL9 and CXCL10 inhibits T cell trafficking, while upregulation of VEGF and TGF-β prevents T cell infiltration into the tumor." (PMID 41514645, 2025). "In this study, we found that IFN-I is related to CXCL9+ macrophages and CD8+ T cell immunity in NPC, and then identified that tumor-intrinsic USP5 is a key suppressor of this IFN-I–activated antitumor immunity." (PMID 41321309, 2025). "As confirmed in Patient 7, upregulation of CXCL9+ and CXCL13+ cells and localization within the tumour were confirmed in all post anti-PD-L1-CRT tissues." (PMID 40670667, 2025). "For example, CXCL1 and CXCL2 promote angiogenesis, whereas CXCL9 and CXCL10 exhibit angiostatic effects, which can influence the tumor's vascularization and growth." (PMID 40242222, 2025). "The IFN-γ signaling pathway, activated by T cells and NK cells, induces CXCL9 and CXCL10 expression in tumor and stromal cells." (PMID 40475782, 2025). "CXCL9/10/11 levels were markedly lower than SPP1, consistent with the downregulation of these three chemokines by tumor cell-secreted factor(s) in short-term stimulation of control monocytes." (PMID 40176808, 2025). "In cancer cells, autocrine CXCR3 signaling promotes metastasis and growth through AKT signaling, while CXCL9 and CXCL11 can inhibit tumor growth by facilitating immune cell infiltration." (PMID 39940842, 2025). "Signature gene analysis of IFN‐Mac_CXCL9 revealed 108 significantly up‐regulated genes in tumour‐infiltrating cells including HLA‐A, HLA‐DRB1 and interferon‐regulated genes (CXCL9, CXCL10 and IL4I1)." (PMID 41275425, 2025). "In such cases, therapeutic strategies that restore chemokine signaling (e.g., CXCL9/10-CXCR3 axis), enhance antigen presentation, or normalize tumor vasculature are essential to reinvigorate TIL activity within the TME." (PMID 40475782, 2025). "Chemokines such as CXCL4, CXCL9, CXCL10, CXCL11, CXCL13, and CCL5 contribute to the accumulation of CD8+ T cells and B lymphocytes in tumor tissues and inhibit angiogenesis." (PMID 41223031, 2025).
tumor (continued). "This is characterized by enhanced expression of pro-inflammatory cytokines such as IFN-γ, which can also stimulate the secretion of chemokines (e.g. CXCL9, CXCL10, and CXCL11) to amplify the anti-tumour immune response." (PMID 40510180, 2025). "Tumours can also act more indirectly, for example by suppressing the production of chemo-attractants such as CXCL9 and CXCL10, which thereby limits the migration of T-cells into the tumour microenvironment 64,65." (PMID 40768308, 2025). "Epigenetic reprogramming can sensitize cancer cells to immune checkpoints blocking therapies through the upregulation of immunostimulatory cytokines (e.g. CXCL9 and CXCL10) that recruit T lymphocytes to the tumor site." (PMID 40317004, 2025). "In contrast, IFNγ stimulation significantly increased TAM CXCL9 expression, with the greatest upregulation evident in Ly6C+MHC-II+ mdTAM, mirroring the effects on anti-PD-L1-treated tumours in vivo." (PMID 40523200, 2025). "Silences tumor suppressor pathways (drives inflammation through cytokines such as TNF-α and CXCL9), promotes epithelial-mesenchymal transition." (PMID 39973938, 2025). "Numerous studies have reported significant associations between the expression levels of inflammatory cytokines—including IL-6, CXCL9, TNF-α, IL-17A, and IL-32—and LUAD tumor stage, metastasis, and prognosis." (PMID 40136462, 2025). "The tumor microenvironment in this subtype features elevated levels of IFN-γ, CXCL9, and CXCL10, alongside notable infiltration of CD8+/CD4+ T cells." (PMID 40260289, 2025). "In contrast, ELR-negative chemokines such as CXCL9, CXCL10, and CXCL11 are classically viewed as anti-tumor agents due to their angiostatic and immune modulatory effects mediated by their shared receptor, CXCR3." (PMID 41516196, 2025). "RNA sequencing data showed a significant upregulation of genes known to increase T and B cell trafficking to tumours (CCL19, CXCL9) and tumour cell killing (GZMB) in these “elite responders”." (PMID 41226343, 2025). "CXCL9 and CXCL10 are capable of chemoattracting the lymphocytes leading to the tumor-infiltrating lymphocytes (TILs) phenomena." (PMID 39996769, 2025). "Tumor microenvironment analysis revealed remodeling of the myeloid compartment, significant induction of IFN-γ, TNF-α, and CXCL9 and broad gene expression reprograming." (PMID 40280970, 2025). "CXCL9, an IFN-γ-inducible chemokine that recruits CXCR3+ effector T and NK cells, is central to anti-tumor immunity." (PMID 41357226, 2025). "Normal tissues exhibited higher levels of S100A9, FTCD, POF1B, IL7R, and MYO1E, whereas tumor tissues showed increased expressions of SPINK1, CXCL9, AGFG1, and IQGAP3." (PMID 41578779, 2025). "Taken together, our results indicate that depletion of tumor-intrinsic USP5 triggers the transfer of p-STATs from tumor cells to macrophages, inducing CXCL9+ macrophage and CD8+ T cell antitumor immunity." (PMID 41321309, 2025). "Our initial focus was on understanding the mechanisms through which CXCL9+ cells and CXCL13+ cells are attracted to the tumour vicinity and evaluating chemokines, interleukins, and IFN receptors." (PMID 40670667, 2025). "Unfortunately, our results showed decreased Cxcl9/10/11 expression in Tnfrsf14KD‐ID8 cells and an elevated proportion of ascitic CTLs, NKs, NKTs, and Th1 cells in Tnfrsf14KD‐ID8 tumor‐bearing mice." (PMID 40105652, 2025). "Elevated CXCL9 expression correlates with increased infiltration of CD8+ T cells and other effector immune populations, reflecting a more immunologically active tumor status." (PMID 41462979, 2025). "CXCR3 ligands, such as CXCL9, CXCL10, and CXCL11, are mainly produced by monocytes, endothelial cells, and tumour cells and are crucial for regulating anti-tumour immunity." (PMID 40361472, 2025). "Mechanistically, we show that IGF blockade promotes macrophage and fibroblast production of the chemokines CXCL9 and CXCL10 to facilitate CD8+ T cell recruitment and trafficking towards the PDAC tumour." (PMID 39165364, 2024).
tumor (continued). "Some tumor treatments to induce CXCL9 and CXCL10 expression in tumor cells also potentially benefit tumor immunotherapeutic efficacy when administered by a combination strategy." (PMID 38953994, 2024). "Research has demonstrated that CXCL9 plays a role in attracting immune cells, such as CD8+ T cells, to the site of the tumor." (PMID 38098230, 2024). "The stromal predilection appears to be driven by low tumor cell MHC class II (HLA-DR), CXCL9, and CXCL10 expression as increased tumor cell expression of these correlated with significant increases in parenchymal T cell infiltration." (PMID 38822345, 2024). "Cxcr3, a chemokine receptor with anti-tumor effects expressed in effector CD8+ T cells, Th1 cells, and NK cells, interacts with its ligands Cxcl9, Cxcl10, and Cxcl11, promoting immune cell recruitment to TME." (PMID 38622609, 2024). "CXCL9, CXCL10, and CXCL11 are mainly secreted by myeloid lineages and tumor cells in the TME responding to IFN-γ, and this process is synergistically enhanced by TNF-α." (PMID 39076974, 2024). "The expression of CXCL9 and SPP1 was employed to define TAM polarization, characterizing their roles in tumor promotion or suppression." (PMID 38222314, 2024). "In the invasive margin of CRC liver metastasis (CRC-L), CCL5+CD4 and CD8 cells, recruited by myeloid-derived CXCL9 and CXCL10, attract macrophages promoting invasion and tumor growth by MMP." (PMID 39100682, 2024). "Initially TNF-γ works by recruiting cohorts (CXCL9, CXCL10, CXCL11, and CXCR3) to promote antigen presentation (MHC class I and class II), T-cell initiation and activation (CD80, CD86, and CD40), and tumor cell killing (Fas and FASL)." (PMID 39835116, 2024). "In contrast to tumor gene expression, the levels of systemic CCL5, CXCL9 and CXCL10 in baseline serum samples were similar among all patients, regardless of their response to anti-HER2 antibody-based neoadjuvant treatment." (PMID 38167224, 2024). "CXCL9, also known as monokine induced by IFN‐γ, is primarily responsible for inducing lymphocytic infiltration into tumors, leading to the suppression of tumor growth." (PMID 38434763, 2024). "The chemokines CXCL9, CXCL10, and CXCL11 in the tumor micro-environment are chemo-attractants for activated NK and Th1 cells and mediate antitumor immunity." (PMID 38302476, 2024). "Chemokines and cytokines, such as IFN-γ, CXCL9, and CCL20, are related to the recruitment of CD4+ and CD8+ T cells, so the lack of chemokines and cytokines may lead to impaired recruitment of immune cells, thereby causing an immunosuppressive tumor microenvironment." (PMID 38982511, 2024). "Single-cell RNA-sequencing analysis of patient tumor-infiltrating lymphocytes revealed that CXCR3 was expressed by CD8+ and CD4+ T cells, whilst CXCL9 and CXCL10 were predominantly expressed by macrophages following dual ICI treatment." (PMID 38533720, 2024). "Upregulation of genes that encode for proteins known to increase T and B cell trafficking to tumors (CCL19, CXCL9), migration (MACF1) and tumor cell killing (GZMB) correlated with responses." (PMID 38519913, 2024). "By altering the expression of chemokines such as CXCL9 and CCL2, radiotherapy can modulate the TME, increasing the likelihood of an effective immune response against the tumor." (PMID 39578426, 2024). "The levels of CXCL10, CXCL9, and CXCL11 in the tumor correlates with the concentration of intratumoral cytotoxic lymphocytes (CTLs) and reduced tumor angiogenesis." (PMID 38726320, 2024). "Studies have found that IFNG, CXCL9, and CD274 expression in tumor specimens correlate to stronger immunotherapy responses." (PMID 38265267, 2024). "IT CXCL9/10-DC leads to enhanced T cell infiltration and activation in the TME and tumor inhibition in murine NSCLC models." (PMID 38518770, 2024). "Epigenetic silencing of the tumor Th1-type chemokines CXCL9 and CXCL10 also contributes to severe T-cell infiltration and greater tumor evasion." (PMID 38791528, 2024).
tumor (continued). "In studies involving Burkitt’s lymphoma in nude mice, CXCL9 and CXCL10 have been reported to induce tumor necrosis." (PMID 39409924, 2024). "The CXCL9/CXCL10/CXCR3 axis plays a role in recruiting tumor-infiltrating lymphocytes (TILs) to tumors across various cancers, indicating a potential anti-tumor function." (PMID 39409924, 2024). "The CXCL9/CXCL10-CXCR3 axis is crucial for NK cell-DC-CD8+ T cell crosstalk and anti-tumor immune response." (PMID 39114657, 2024). "Some chemokines play important roles in recruiting immune cells, such as CXCL9 and CXCL10, which can recruit NK cells, NKT cells, and macrophages to the TME and increases the cytotoxic activity against tumor cells." (PMID 39139561, 2024). "The CXCL9, CXCL10, and CXCL11-CXCR3 axes are reported to regulate cytotoxic lymphocyte migration and mediate a tumor suppression response." (PMID 39076974, 2024). "In pre-clinical studies, CD206 TAMs were found to be the primary source of CXCL9—the well-established chemoattractant for CXCR3-expessing NK and CD8 T cells, driving anti-tumor immunity." (PMID 38893266, 2024). "CXCL9/10/11 do not only recruit effector CD4+ and CD8+ to tumor sites but also inflammatory sites in the body." (PMID 38928238, 2024). "The CXCL9, CXCL10 and CXCL11/CXCR3 axes have been demonstrated to regulate immune cell migration, differentiation, and activation, leading to tumour suppression." (PMID 39233332, 2024). "To achieve this, we measured the levels of chemokines (CCL5, CXCL9, and CXCL10) in tumor tissues using ELISA across different treatment groups." (PMID 38931345, 2024). "Following dual PD-1/CTLA-4 blockade, macrophages secrete CXCL9 and CXCL10, increasing tumor infiltration of CD8+ T cells." (PMID 39114657, 2024). "We find that IT CXCL9/10-DC augments T cell infiltration and activation in the TME, leading to effective tumor inhibition in multiple syngeneic murine NSCLC models." (PMID 38518770, 2024). "CD4+ Th1-polarized effector memory cells expressing CXCR3 and CCR5, the receptors for CXCL9/10/11 and CCL5, respectively, are another significant component of tumor-infiltrating lymphocytes (TILs)." (PMID 39114657, 2024). "CXCL9/10/11 are interferon-induced chemokines that recruit effector CD8+ and CD4+ T cells to the tumor microenvironment by binding them to their cognate receptor CXCR3." (PMID 38928238, 2024). "Our data suggest that C5aR suppresses CXCL9 secretion from macrophages, thereby hindering the recruitment of CD8+ T cells, thus impeding host antitumor immunity and promoting tumor progression." (PMID 38098230, 2024). "At the same time, it promoted the secretion of CXCL9 and CXCL10 to recruit NK cells to the tumor, killing tumor cells." (PMID 38347129, 2024). "In this research, the ERGS was composed of 8 ERGs (CXCL9, CYP17A1, DRGX, ENTHD1, HAS1, LAIR2, RETN, and SPHKAP), some of which were pivotal to the tumor progression." (PMID 38600248, 2024). "Subsequently, by using transcriptomics and proteomics techniques, CXCL9 and PLEC were respectively located as the key factors for the tumor-promoting effect of EpOMEs in TNBCs." (PMID 39695149, 2024). "CXCL9 and CXCL10, by binding to their receptor CXCR, can attract and activate anti-tumor immune cells such as CD8+ T cells and natural killer (NK) cells, thereby enhancing their ability to eliminate tumor cells." (PMID 38277205, 2024). "Chemokines chemokine C-C motif ligand (CCL) 9 (CCL9), CCL17, CCL20, CXCL5, CXCL9, and CXCL10 secreted by hepatocytes regulated tumor progression by acting on CD8+ T cells." (PMID 39346534, 2024). "For example, CXCR3, when expressed by CD8+ T cells, allows their ligands CXCL9 and CXCL10 to guide the migration of CD8+ T cells to tumor tissue, resulting in an anti-tumor effect." (PMID 39769501, 2024).